CASP6 (caspase 6)
Diseases named in the same sentence as CASP6 in open-access papers (continued):
Sharing a sentence is not in itself a finding about the gene and the disease.
skin infection (1 paper, 2022). An inflammatory process affecting the skin, caused by bacteria, viruses, parasites, or fungi. "We first used the skin infection model and infected WT and Casp6–/– mice with the HSV-1 ΔUs3 strain." (PMID 36146839, 2022).
small intestinal tumors (1 paper, 2025). "We found that Caspase‐1, Caspase‐6, and Caspase‐8 were expressed and activated in mouse CRC and small intestinal tumors." (PMID 40213993, 2025).
tauopathies (1 paper, 2024). "Given caspase-6 cleaved tau abundance in AD but scarcity in 4R tauopathies, it is worth testing if a CSF assay for caspase-6 cleaved tau performs better in discriminating AD from 4R tauopathies than phospho-tau based assays." (PMID 38419122, 2024). "This review will examine the evidence of caspase-cleaved tau contribution to tauopathies, with a specific emphasis on the more recent advancements related to caspase-6 cleaved tau." (PMID 38419122, 2024). "Recent findings indicate that caspase-6 cleaved tau D13 and D402, commonly present in AD neurons, but rarely in 4-repeat tauopathies, only partially overlap with phospho-tau in the same neuron." (PMID 38419122, 2024). "Caspase-6 activation levels were also seen at much lower levels in 4R-tauopathies than in AD." (PMID 38419122, 2024). "Despite confluent evidence of the role of caspase-6 activation and caspase-6-cleaved in AD pathogenesis, only recently monoclonal antibodies against these tau specimens became available to directly investigate the frequency of tau D13 and D402 in tauopathies." (PMID 38419122, 2024). "Finally, in addition to developing specific inhibitor drugs for caspase-6, existing drugs could be repurposed to inhibit caspase-6 cleaved tau in AD and other tauopathies." (PMID 38419122, 2024). "While the precise role of caspase-1 in AD neuropathology remains unclear, compelling evidence suggests that targeting caspase-1 could be a viable therapeutic approach for addressing AD and possibly other tauopathies, alone or combination with drugs targeting Nlrp1 and caspase-6." (PMID 38419122, 2024).
thyroid cancer (1 paper, 2022). "Protein expression of three PRGs was then determined, where CASP6 and IL18 were increased in thyroid cancer tissues, while CASP9 was down-regulated, which was also consistent with the bioassay results." (PMID 36675746, 2022).
uterine corpus endometrial carcinoma (1 paper, 2020). A endometrial carcinoma (disease) that involves the body of uterus. "The Arg-378Trp mutation in caspase-2, or Arg-207Stop in caspase-3, or Arg-220Trp in caspase-6 were found in uterine corpus endometrial carcinoma and is probably involved in apoptotic cell death disturbances and tumorogenesis." (PMID 33011746, 2020).
viral encephalitis (1 paper, 2024). Encephalitis resulting from viral infection. "Surprisingly, other proapoptotic factors including Casp3, Casp6 and Bax were largely unchanged between groups indicating only select cell death pathways may be activated during viral encephalitis." (PMID 38658802, 2024).
vitiligo (1 paper, 2022). Generalized well circumscribed patches of leukoderma that are generally distributed over symmetric body locations and is due to autoimmune destruction of melanocytes. "Further analysis of melanocytes revealed strong pyroptosis responses existed in patients with vitiligo.Results demonstrated that CASP1, CASP4, CASP6, CASP8, and GSDMD expression was significantly upregulated in melanocytes of patients with vitiligo." (PMID 35962439, 2022).
tumor (67 papers, 2001 to 2025). "According to the literature, Casp-6 expression is associated with nuclear laminas in cancer cells, characterized by tumor initiation." (PMID 39062149, 2024). "While CASP6 has been associated with pyroptosis and tumor prognosis, its role in OA requires further investigation." (PMID 37853066, 2023). "In BRCA, CASP6 inactivation or overactivation may be associated with tumor suppression or cell survival, respectively." (PMID 40065765, 2025). "This association suggested that an increased expression of caspase-6 and localization to cytoplasm may be involved in lamin A/C degradation prior to nuclear envelope structural defects, aneuploidy and chromosomal instability involved in tumor cell initiation." (PMID 30450209, 2018). "Through its regulation of PANoptosis, CASP6 plays a vital role in tumorigenesis in humans and mediates anti-tumour immunity." (PMID 38169587, 2024). "The lncRNA PVT1/hsa-miR-16-5p/CASP6/CASP8 regulatory axis plays an vital role in regulating the anti-tumor immune responses for PAAD." (PMID 36882663, 2023). "We then investigated the biological functions of CASP6 and the relationship between CASP6 expression and the tumor microenvironment and immunocyte infiltration." (PMID 36119521, 2022). "Increasing evidence has revealed that CASP6 is involved in carcinogenesis and progression by regulating the apoptosis and metastasis of tumours." (PMID 34226539, 2021). "Immunohistochemistry staining further confirmed that oral gavage of TVB‐2640 down‐regulated the expression of Ki‐67 and up‐regulated that of p27 and caspase‐6 in tumor tissues." (PMID 33665967, 2021). "Compared to the control group, both nsPEF- and everolimus-treated tumours showed increased expression of caspase 3, caspase 6, and Bax, and decreased expression of Bcl-2." (PMID 28054548, 2017). "The results implied that the tumor apoptosis was induced by the upregulated expression of HtrA2, caspase 6, caspase 7, caspase 10, Gas2, and Lamin A." (PMID 27275821, 2016). "As expected, VEIDase Casp6 activity levels and pro-Casp6 and active Casp6 p20 subunits were significantly higher in KI/Cre than in the control mice normal and tumor tissues." (PMID 25470254, 2014). "To further investigate the effect of Caspase‐6‐mediated GSDMC activation on tumor development, we intraperitoneally injected vehicle or 5mg kg−1 Caspase‐6 inhibitor Z‐VEID‐FMK every other day for 30 days, starting at day 40 of the AOM‐DSS induced CRC mouse model." (PMID 40213993, 2025). "Theoretically, GSDMC can sensitize tumor cells to the treatment of any drugs that could activate caspase-6 or caspase-8, or could stimulate antitumor immunity response." (PMID 37883181, 2024). "Therefore, studies have reported the functional significance of CASP6 in PANoptosis and its impact on cancer development, indicating a potential therapeutic target and strategy for tumor treatment." (PMID 38169587, 2024). "Besides, to further confirm the tumor-promoting effect of CASP6 in PAAD, we carried out a series of experiments in vitro." (PMID 36882663, 2023). "CASP4, CASP6, CASP8, IL18, and PYCARD were associated with clinical stage, which means that IL18 and PYCARD may be involved in tumor progression." (PMID 36882663, 2023). "Tumor cells were positive for 10E4, heparinase and caspase-6." (PMID 35626270, 2022). "Moreover, the activation of caspase-6 and -8 (as inducers of programmed cell death) in tumour epithelial cell lines confirms the expected – via apoptosis – mechanism of action of the investigated compounds." (PMID 33390035, 2021). "In addition, caspase-6 can also be involved in cancer progression by regulating tumor apoptosis and metastasis." (PMID 34899864, 2021). "In addition to caspase-2, other caspases such as caspase-6, -7, and -8 also act as tumor suppressors, although the genetic mechanisms underlying the activation of these caspases and their relevance to tumor suppression remain to be elucidated." (PMID 32438737, 2020).
tumor (continued). "The DNA damage by radiation may result in the cell cancelation; in addition, the reduction of caspase-3 and caspase-6 would lead to the mass proliferation of tumor cells." (PMID 26193298, 2015). "DR5 expression, however, and the activation of caspase-6 which is directly implicated in this process, were not altered in any tumor cell line." (PMID 24618889, 2014). "Moreover, the expressions of CASP6, GPX4, GSDMC, and NOD2 could increase the susceptibility of tumor cells to paclitaxel, 5-fluorouracil, dasatinib, and gefitinib." (PMID 35368686, 2022). "CASP6 was suggested that may be related to apoptosis which attends to the occurrence and development of cancer by promoting the activation of the ways of programmed cell death in tumor issues." (PMID 36092153, 2022). "The results showed tumours with high expression of GSDMB and caspase-6 to be mainly immune inflammatory tumours, with those having poor expression of GSDMB and caspase-6 being mostly immune-desert tumours." (PMID 36702978, 2023). "Compared with normal tissues, CASP6, GPX4, NOD2, and WNK1 were upregulated in HCC samples, presenting low- to medium-intensity expressions, and high expression of CYCS emerged in tumor tissues." (PMID 35368686, 2022). "Similar results were evident in the present study, in which the genetic expression of three genes (AIM2, CASP6, and CASP8) was upregulated in tumor tissues and was validated as protective factors in the multivariate Cox regression analysis." (PMID 35846123, 2022). "Based on the hazard ratio (HR), the downregulated PLCG1, CASP6, CASP4, and AIM2 were considered tumor suppressors, whereas the upregulated PRKACA, NLRP9, and BAK1 were regarded as oncogenes." (PMID 34805183, 2021). "IHC also showed that caspase-1, caspase-3, caspase-6, caspase-9, and PARP proteins were mainly expressed in the cytoplasm of tumor tissue." (PMID 24204937, 2013). "CASP8, CASP6, GSDME, NOD1, and GPX4 were significantly upregulated in tumor tissues compared to the normal tissues, whereas IL6, IL1B, NLRP3, and NLRC4 were downregulated, suggesting that pyroptosis-related genes play important roles in tumor progression and prognosis." (PMID 35559014, 2022). "Crucially, we observed the upregulation of the cleaved caspase 9 fragment at 35 kDa as well as the cleaved caspase 6 fragment at 15 kDa, but not of the full-length proteins in the hot tumor subgroup." (PMID 36139700, 2022). "Notably, the expression levels of 5 PRGs (CASP1, CASP3, CASP6, GSDMB, and GZMA) were lower in both CRC tissues and the high-stage group, suggesting that their potential function as tumor suppressors in CRC tumorigenesis and development." (PMID 35937993, 2022). "First, PDT can activate caspase-8 and caspase-9, and then the active form of caspase-8 and caspase-9 initiates caspase-3 and caspase-6 activation to subsequently activate the remainder of the caspase cascade, which degrades PARP, and finally leads to apoptosis of tumor cells." (PMID 24204937, 2013). "At variance with other tumour types, however, no cleavage of executioner caspase-6 or -7 became evident in our RCC model system." (PMID 12771998, 2003). "In this investigation, we determined three pyroptosis-related genes including CAPN1, BNIP3, and CASP6 as prognostic signatures of NSCLC based on the expression profile with 146 pyroptosis-related genes from the TCGA database, which are overexpressed in the tumor tissues." (PMID 36092153, 2022). "Therefore these results indicate that Casp6 overexpression in the colon has no impact on tumor development in the AOM/DSS-induced colon carcinogenesis." (PMID 25470254, 2014).
tumor (continued). "In the caspase family, caspase-1, caspase-3, caspase-6, and caspase-9 are major cascade activation proteins, and PDT initiates the apoptosis cascade reaction primarily by activating caspase-dependent intrinsic and extrinsic pathways; this cleaves PARP, ultimately leading to apoptosis of tumor cells." (PMID 24204937, 2013).
cancer (37 papers, 2010 to 2025). A tumor composed of atypical neoplastic, often pleomorphic cells that invade other tissues. "In our study, drug-sensitivity analysis revealed that the expression of NLRP7, NLRP2, NOD1, and CASP6 was positively correlated with some or most drugs in the cancer therapeutic response portal database." (PMID 34226539, 2021). "Therefore, the loss of Casp6 activation may significantly contribute to the cancer state in colon." (PMID 24265764, 2013). "To determine whether ZBP1-derived PANoptosome assembly was triggered by chemotherapy in cancer patients, we performed PLA assay in colonic tissues to examine the association between ZBP1 and RIPK3 or Casp-6, respectively." (PMID 39465258, 2024). "Among them, apoptosis-related genes, such as Casp6, Bak1 and Casp8 are up-regulated, suggesting that the GOD@POMs + laser treatment could cause cancer cells apoptosis." (PMID 36435848, 2022). "It remains speculative whether increased expressions of CASP3, CASP6, and CASP8 may be associated with enhanced pyroptosis and cell death, thereby reducing the cancer’s aggressiveness." (PMID 35928267, 2022). "The results show that expression of ELANE, PRKACA, CASP3, CASP9 and CASP6 was related to the efficacy of various anticancer drugs, indicating that pyroptosis genes may participate in pan‐cancer signalling pathways and affect the efficacy of anticancer drugs." (PMID 34816605, 2022). "In caspase-3 deficient cancer cells such as MCF-7, caspase 6, 8 and 9 could be involved in apoptosis." (PMID 32847047, 2020). "However, in less well-differentiated areas, active Casp6 is strongly decreased consistent with the higher levels of proCasp6 in cancer tissues that indicate less activation of Casp6." (PMID 24265764, 2013). "Caspase-6 signalling induced by an EGFR inhibitor might contribute to the induction of apoptosis in SN38-resistant cancer cells." (PMID 21997136, 2011). "However, few studies pertaining to caspase-6 in malignant tumors exist." (PMID 35846123, 2022). "As caspase-6 mutations also occur rarely in human cancer, it can be summarized that executioner caspases are generally not mutated in the majority of human cancers." (PMID 24281211, 2010). "Several genes regulated by HCQ in Ca9-22 cells have been identified as potential cancer therapy targets, including TNFRSF11B, CASP6, BIRC2, and BIRC5." (PMID 41303490, 2025). "Correlation analysis demonstrated that the expression of most of the PANoptosome components was positively correlated with CNV levels in many cancers (such as BRCA, HNSC, LUSC, and OV), especially for FADD, RIPK1, and CASP6." (PMID 38436818, 2025). "In another study, CASP6 facilitated ZBP1-mediated inflammasome activation, PANoptosis cell death, and host defense, opening additional avenues for treating cancer, infectious, and autoinflammatory diseases." (PMID 38169587, 2024). "Apoptosis (e.g., BID, CASP6, etc.)and aminoacyl-tRNA biosynthesis (e.g., CARS2 and AARS2) were predominant in the D4 (HGIN stage), suggesting cancer malignancy." (PMID 36991000, 2023). "Significantly upregulated PRGs included PYCARD in 12 cancers; GSDMB in 10 cancers; IL18 in 9 cancers; GSDMD, CASP8, GZMB, and GPX4 in 8 cancers; AIM2 and CASP6 in 7 cancers; GZMA in 6 cancers; GSDME, CASP4 and DHX9 in 5 cancers; GSDMA and GSDMC in 4 cancers." (PMID 36605187, 2022). "The lncRNA MVIH is involved in drug resistance in NSCLC, and knockdown of MVIH restored drug sensitivity of cancer cells to cisplatin (DDP) by inducing apoptosis via upregulation of caspase-3, caspase-6 and cleaved PARP." (PMID 35379783, 2022). "Relative PAM, STC1, and HDAC4 expression were down-regulated, whereas CASP6, CHST6, SLC16A3, TPI1, KDELR3, VCAN, and CLDN9 were highly expressed in carcinoma tissues compared to the para-carcinoma tissues." (PMID 33424916, 2020).
cancer (continued). "These include cancer hallmarks of various types: oncogenes (BCL2, BRAF), caspases (CASP6/7), transcription factors (E2F3), cell cycle genes (CDC42, CDK2, CDKN2A), cancer related kinases (JAK2/3, MAPK4/6/14) and DNA repair genes (BRCA1, PARP1 and RAD50)." (PMID 28059167, 2017). "Mechanistically, under hypoxia and low‐glucose condition, GSDMC2/3/4 are directly activated by Caspase‐6, but not by Caspase‐8, as previously reported in other cancers." (PMID 40213993, 2025). "We observed that NLRP7 (n = 8), AIM2 (n = 10), CASP8 (n = 6), GSDMA (n = 5), GSDMB (n = 8), and GSDMC (n = 12) mainly showed hypomethylation in most cancers, and PLCG1 (n = 11), NLRP6 (n = 13), ELANE (n = 11), CASP6 (n = 5), NLRC4 (n = 12), and PYCARD (n = 8) showed hypermethylation in most cancers." (PMID 35246158, 2022). "In cancer cells the concept of lamin A/C cleavage by caspase-6 prior to apoptosis is no longer applicable due to the absence of lamin A. Indeed, in cancer cells, there is an alteration of cell proliferation and apoptotic markers." (PMID 30450209, 2018). "Our study also showed in some cancer cell lines the degradation of lamin A is related to active caspase-6 and can be abolished with caspase-6 inhibitor in OVCAR3 but not in OVCAR5 nor A2780 cell lines (data not shown)." (PMID 30450209, 2018). "The results showed that HOSE cells expressed lamin A/C and no or low level of active caspase-6 while cancer cells highly expressed caspase-6 and no or low level of lamin A/C." (PMID 30450209, 2018). "Similarly, inhibition of Casp1 and Casp6 by methylene blue could have beneficial effects by reducing inflammatory processes and axonal degeneration, but inhibition of Casp3 could alter neuronal function or promote cancer cell survival and be detrimental to tissue homeostasis." (PMID 26400108, 2015).